IRF7 (interferon regulatory factor 7)
Diseases named in the same sentence as IRF7 in open-access papers (continued):
Sharing a sentence is not in itself a finding about the gene and the disease.
leukemia (12 papers, 2021 to 2025). A malignant (clonal) hematologic disorder, involving hematopoietic stem cells and characterized by the presence of primitive or atypical myeloid or lymphoid cells in the bone marrow and the blood. "This miRNA participates in the growth and differentiation of hematopoietic stem cells and is essential for the maturation of T lymphocytes through interferon regulatory factor 7 (IRF7)-mediated signaling, but its deregulation has been associated with leukemia." (PMID 38203290, 2023). "In leukemia mouse models, interferon regulatory factor 7 (IRF7) induces M1 polarization of TAMs, which is associated with prolonged survival of leukemia mice." (PMID 34359674, 2021). "On the other hand, Interferon regulatory factor 7 (IRF7) has been found to have tumor suppressor properties in AML since the IRF7 loss accelerates acute myeloid leukemia progression while IRF7 overexpression in decreased leukemia stem cell (LSC) levels." (PMID 36941700, 2023). "Meanwhile, sorafenib synergizes with T cells by downregulating ATF4 expression, leading to the activation of the IRF7–IL-15 axis in leukemia cells." (PMID 41312168, 2025). "Previous research also identified that targeting IRF7‐SAPK/JNK pathway to induce M1 characteristics in TAMs could be a potential target for macrophage based immuno‐therapy strategy against leukemia." (PMID 37366304, 2023). "Therefore, the targeting of the IRF7-SAPK/JNK pathway to induce M1-like characteristics may contribute to prolonging survival in leukemia mice." (PMID 38779660, 2024). "Taking away the ATF4-mediated blockade, sorafenib allowed IRF7 activation and caused IL-15 transcription in the leukemia cells which caused an increase of CD8+ CD107a+ IFNγ+ T cells, which was connected to the increased elimination of leukemia cells by activated donor T cells." (PMID 35460465, 2022). "Subsequent studies have confirmed that IRF7 can activate the SAPK/JNK pathway in macrophages to promote their polarization towards the M1 phenotype, thereby prolonging the survival time of leukemia mice." (PMID 38779660, 2024). "The researchers also found that repolarization of LAMs through targeting of the SAPK/JNK pathway and IRF7-SAPK/JNK pathway by interferon regulatory factor 7 (IRF7) can prolong the survival of AML mice, providing regarded a new immunotherapy strategy against leukemia." (PMID 35875135, 2022). "Nevertheless, the role of IRF7 in leukemia has not been established." (PMID 35256780, 2022).
atherosclerosis (11 papers, 2015 to 2025). A disease characterized by the build-up of fatty material and calcium deposition in the arterial wall resulting in partial or complete occlusion of the arterial lumen. "By identifying and validating the association of hub genes, such as FHOD1 and IRF7, with SMC-derived macrophages, we provide a new conceptual framework that parallels oncogenic processes in atherosclerosis." (PMID 41262249, 2025). "This study successfully identified key genes associated with EndMT-related atherosclerosis, such as CD68, TLR2, MYD88, IRF7, STAT1, and IL1B, all of which demonstrate substantial diagnostic potential for detecting atherosclerotic plaques." (PMID 38268851, 2023). "Understanding how these genes regulate SMC-to-MAC transitions may reveal new mechanisms of SMC plasticity and vascular inflammation, highlighting FHOD1 and IRF7 as potential therapeutic targets to mitigate vascular remodeling and atherosclerosis progression." (PMID 41262249, 2025). "Given that IRF7 was not specific for plaque T cells in two datasets and had been previously implicated in atherosclerosis by influencing macrophage inflammation and lipid homeostasis, we excluded it from further analysis." (PMID 41039608, 2025). "Interestingly, several of these transcription factors, including RUNX3, STAT1, IRF7, and the Th2 hallmark GATA3, had already been implicated in lesion formation in experimental models of atherosclerosis." (PMID 41039608, 2025). "To further investigate the role of IRF7 and FHOD1 in atherosclerosis, we measured their expression in both human and mouse atherosclerotic tissues." (PMID 41262249, 2025).
colorectal cancer (11 papers, 2014 to 2025). A primary or metastatic malignant neoplasm that affects the colon or rectum. "Our study aimed to examine potentially functional genetic variants in interferon regulatory factor 3 (IRF3), IRF5, IRF7, type I and type II IFN and their receptor genes with respect to colorectal cancer (CRC) risk and clinical outcome." (PMID 25350395, 2014). "Similarly, in colorectal cancer, brief exposure to low doses of 5-AZA-CdR can induce dsRNA expression, activating the cytoplasmic pattern recognition receptor MDA5 and subsequently engaging downstream effectors MAVS and IRF7 to target colorectal cancer cells." (PMID 39329125, 2024). "Evidence indicates that the expression of IFI35 in murine colorectal cancer cells is regulated by IFN-γ, with dependencies on STAT1 and IRF-7, thus establishing the IFN-γ/JAK/STAT1/IRF7/IFI35 pathway." (PMID 40909948, 2025). "AZA treatment in colorectal cancer has been reported to promote the expression of interferon-response factors like OASL and IRF7 by inducing up-regulation of dsRNA and stimulation of the MDA5/MAVS/IRF7 pathway." (PMID 35438143, 2022). "However, it is imperative to note that the IFN-γ/JAK/STAT1/IRF-7/IFI35 pathway, as characterized in this study, has yet to be directly validated in vivo within a mouse model of colorectal cancer." (PMID 40909948, 2025). "To create an endogenous type I IFN reporter, we chose the colorectal cancer cell line HCT116, which is highly efficient for CRISPR-based gene editing, and surveyed IFNα induction of canonical type I IFN target genes (IFIT1, IFIT2, IFIT3, IFI27, IRF7, OASL, RSAD2)." (PMID 38358346, 2024). "In colorectal cancer cells, TIP60 also exerts an anti-inflammatory response by activating the expression of SUV39H1 and SETDB1, two histone H3K9 methyltransferases, which in turn repress the transcription of retrotransposon elements to contain STING/IRF7-mediated inflammation." (PMID 32626711, 2020).
lung carcinoma (11 papers, 2011 to 2025). "The disruption of the IFN pathway in lung cancer cell lines and primary tumor tissues is caused by epigenetic silencing of critical interferon responsive transcription factors IRF7 and/or IRF5." (PMID 22194884, 2011). "Altogether the selective loss of viral protection in lung cancer cells was related to epigenetic inactivation of at least one of the IRFs implicating the necessity of both IRF7 and IRF5 to be active for a functional IFN pathway." (PMID 22194884, 2011). "Moreover, transcription factors IRF5 and IRF7 were identified as critical regulators of innate immune system and useful biomarkers for oncolytic virus susceptibility in lung cancer cells as both of them have to be inducible for a functional IFN pathway." (PMID 22194884, 2011). "Although basal levels of most ISGs were reduced in all the lung cancer cell lines compared to normal bronchial epithelial cells, oncolytic viral sensitivity is only associated with polyI:C-inducible expression levels of certain key ISGs such as IRF7 and IRF5." (PMID 22194884, 2011). "Therefore, we investigated whether promoter methylation of IRF7 could also be the cause of IFN pathway disruption in lung cancer cell lines." (PMID 22194884, 2011). "Our microarray data analysis revealed and RT-qPCR confirmed the increased mRNA expression of all of the OAS gene family members (OAS1, OAS2, OAS3, OASL) and XAF1 and IRF7 in the lung cancer cell line A549 after transfection with BNC2." (PMID 28184177, 2017). "We presented evidence that functional inactivation of IRF5 and IRF7 is the major mechanism to disrupt IFN signaling in lung cancer cells." (PMID 22194884, 2011). "We have shown epigenetic silencing of IRF5 and IRF7 at CpG islands of promoter regions in lung cancer." (PMID 22194884, 2011). "Additionally, Irf7 has been shown to play a role in the regulation of inflammation in lung cancer by inhibiting the expression of proinflammatory genes." (PMID 37946128, 2023). "DNA sequencing of sodium bisulfite-treated genomic DNA revealed IRF7 promoter hypermethylation in 2 lung cancer cell lines (CRL5810 and CRL5869), which suggests that epigenetic silencing of IRF7 has played a role in the disruption of IFN signaling in these cell lines." (PMID 22194884, 2011). "Additionally, IRF7 inhibits granulocytic suppressor cells, decreasing lung cancer metastasis." (PMID 41262249, 2025). "However, IRF7 promoter has been found to be hypermethylated in lung cancer." (PMID 30305853, 2018). "AFAP1-AS1 regulates lung cancer proliferation, migration, and invasion through the competitive upregulation of RRM2 to inhibit miR-139-5p, IRF7, and RIG-I-like receptor signaling pathways, or epigenetic inhibition of p21 expression." (PMID 38095636, 2023). "Human lung cancer NCI‐H358 (H358) cells showed significant up‐regulation of DDX58, MDA5, MAVS, IRF7, IFNB, RSAD2, and ISG56, after incubation with immRNA‐loaded RBCEVs." (PMID 35430766, 2022). "The protein levels of PDL1, IRF1, IRF7, STAT1, STAT2, IFNAR1, eIF2α, and ATF4 in the normal and tumor tissues of 27 subjects with lung cancer were determined by Western blot." (PMID 30305853, 2018). "Bisulfite sequencing revealed promoter hypermethylation of either IRF7 and/or IRF5 in several lung cancer cell lines." (PMID 22194884, 2011). "Similar resistance to 5-aza-dC treatment was found for the other IRF7-methylated lung cancer cell line CRL5869 (data not shown)." (PMID 22194884, 2011). "IRF5 and IRF7 protein levels were uniformly not inducible upon polyI:C treatment in all the virus-sensitive lung cancer cell lines." (PMID 22194884, 2011). "However 5-aza-dC treatment failed to reactivate IRF5 or IRF7 expression or rescue lung cancer cells from VSV infection." (PMID 22194884, 2011).
lung carcinoma (continued). "A strong polyI:C-induction of phosphorylated-STAT1 (p-STAT1, Ser727), STAT1, IRF5 and IRF7 protein levels was consistent with the resistance of normal Beas2B cells and the two cancer cells, HTB182 and CRL5928, to VSV infection and vice versa for the viral-sensitive lung cancer cell line." (PMID 22194884, 2011). "Therefore, IRF5 and IRF7 are key transcription factors in IFN pathway that determine viral sensitivity of lung cancer cells; the epigenetically impaired IFN pathway in lung cancer tissues provides potential biomarkers for successful selective killing of cancer cells by oncolytic viral therapy." (PMID 22194884, 2011). "Therefore the methylation IRF7 or IRF5 promoters found in the lung cancer cell lines probably had its origin in the tumor rather than being an event selected during to cell culture." (PMID 22194884, 2011). "Similarly, when we investigated DNA from fresh frozen lung cancer tissues, we observed promoter methylation of IRF7 and/or IRF5, suggesting that their IFN antiviral response was also epigenetically silenced as functional IRF7 and IRF5 are required for an intact IFN pathway." (PMID 22194884, 2011).
prostate carcinoma (10 papers, 2013 to 2025). A carcinoma that arises from epithelial cells of the prostate gland. "In vitro culture of prostate cancer cells stably transfected with IRF7 and in vivo experiments with nude mice, as well as validation with clinical patient samples." (PMID 37251373, 2023). "Overexpression of IRF7 boosts IFN-b production and NK cell activity, reducing prostate cancer metastasis." (PMID 41262249, 2025). "Mirroring the findings from human prostate cancer cell lines, MeT increased expression of ERVs (murine ERV-L, MTA, RLTR1B, and RLTR45), LINE-1 elements, Rig-I and Irf7 in RM1 cells." (PMID 36923279, 2022). "It has been reported that nobiletin inhibits the growth of prostate cancer cells by suppressing TLR4/TRIF/IRF3, TLR9/IRF7 and AKT signaling pathways." (PMID 34548474, 2021). "Overexpression of IRF7 increased IFN-β production and thus significantly enhanced NK cell activity, leading to cytolysis of prostate cancer target cells and exerting an inhibitory effect on bone metastasis of prostate cancer." (PMID 37251373, 2023). "A study showed that overexpression of IRF7 increased IFN-β production and significantly enhanced NK cell activity, leading to cytolysis of prostate cancer cells and exerting a role in limiting bone metastasis of prostate cancer." (PMID 37251373, 2023). "Furthermore, the knockdown of IRF7 and 3—transcription factors of TRAIL and Noxa, respectively —also suppressed the HVJ-E sensitivity of prostate cancer cells, suggesting that RIG-I/MAVS signaling regulates the expression of TRAIL and Noxa via IRF7 and 3 in cancer cells." (PMID 24369016, 2013).
Sepsis (10 papers, 2011 to 2025). Sepsis is defined as life-threatening organ dysfunction caused by a dysregulated host response to infection. "To determine whether IRF7 is associated with the pathogenesis of sepsis, we first monitored the 7-day survival rates of wild-type (WT) and Irf7–/– mice after cecal ligation and puncture (CLP), a gold standard model of sepsis." (PMID 41212050, 2025). "Irf7-deficient mice are more susceptible to polymicrobial sepsis." (PMID 41212050, 2025). "Here, we showed that Irf7 deficiency increased mortality during polymicrobial sepsis." (PMID 41212050, 2025). "Therefore, identifying the underlying mechanism that IRF7 defends against sepsis is important to find new measures for sepsis therapy and new functions of IRF7." (PMID 41212050, 2025). "Consequently, this study delineates IRF7’s functional role and underlying molecular mechanisms using a clinically relevant murine sepsis model and complementary in vitro assays." (PMID 41212050, 2025). "Recombinant adeno-associated virus 9–Irf7–mediated IRF7 overexpression promoted the autophagic clearance of pathogens and improved sepsis outcomes, which may be the mechanism underlying the observed improvement in bacterial clearance." (PMID 41212050, 2025). "The use of RNA-based interference for immunomodulation has also been advocated in bacterial infection-induced sepsis, where in one in vivo study of IRF-7 silencing was shown to arrest hyperinflammation-caused tissue damage in acute pyelonephritis and urosepsis." (PMID 37109050, 2023). "Taken together, these results clearly demonstrated that IRF7 was required for defense against polymicrobial sepsis in mice." (PMID 41212050, 2025). "The results in the WT IN and Irf7–/– IN mice revealed that IRF7 drove macrophages to defend against sepsis." (PMID 41212050, 2025). "IRF7 promotes ferroptosis and M1 macrophage polarization via NF-κB signaling in sepsis-induced ALI, intensifying inflammatory responses and lung injury." (PMID 41039310, 2025). "This indicates that rAAV9-Irf7 mediates sepsis protection in Irf7–/– mice via a mechanism that can be activated by BECN1." (PMID 41212050, 2025). "In conclusion, FGF15 suppresses M1 macrophage polarization and associated inflammatory responses in sepsis by activating the NF2-Hippo pathway, thereby inhibiting H3K18 lactylation-driven Irf7 expression." (PMID 40825908, 2025). "These advances, coupled with emerging immunotoxicity mitigation strategies, provide a robust roadmap for translating IRF7-based therapies into clinical practice for sepsis." (PMID 41212050, 2025). "In this study, we revealed that IRF7 induced autophagy to drive macrophages to execute an antimicrobial defense during polymicrobial sepsis." (PMID 41212050, 2025). "IRF7 drives autophagy in macrophages to eliminate pathogens and finally improve sepsis outcome, suggesting therapeutic potential." (PMID 41212050, 2025). "Next, the potential mechanism by which IRF7 mediates its protective effects against polymicrobial sepsis was investigated." (PMID 41212050, 2025). "IRF7 promotes the autophagic clearance of pathogens in macrophages to defend against polymicrobial sepsis." (PMID 41212050, 2025). "These integrated findings collectively establish IRF7 as a master transcriptional regulator of sepsis-induced autophagy." (PMID 41212050, 2025). "Collectively, IRF7 overexpression represents a potential host-directed therapeutic strategy for preclinical sepsis models, operating independently of antibiotic mechanisms." (PMID 41212050, 2025). "Unexpectedly, the expression of type I IFN genes (Ifna and Ifnb) peaked at the early stage of sepsis, but Irf7 expression was high at the late stage." (PMID 41212050, 2025). "Collectively, our data revealed that IRF7 promoted bacterial killing via autophagy in macrophages during sepsis." (PMID 41212050, 2025). "Taken together, these results suggest that IRF7 promotes bacterial killing during polymicrobial sepsis." (PMID 41212050, 2025).